BRAF (B-Raf proto-oncogene, serine/threonine kinase)
Diseases named in the same sentence as BRAF in open-access papers (continued):
Sharing a sentence is not in itself a finding about the gene and the disease.
tumor (continued). "Indeed, it turned out that although engineering of BRAF T529 gatekeeper mutations does confer vemurafenib resistance in vitro, these mutations have never been reported in tumor samples from BRAF inhibitor-resistant patients." (PMID 25422355, 2015). "Recent findings suggest that inhibition of mTORC1 activity, as measured by tumor levels of Ser240/Ser244-phosphorylated S6 (pS6) is a robust biomarker for the antitumor activity of at least some protein kinase inhibitors such as inhibitors of mutant BRAF and PI3K." (PMID 25015210, 2014). "BRAF:p.V600E mutations were detected in 7 of 16 (43%) group I tumors, but in no group II tumor." (PMID 24529209, 2014). "In addition, almost all patients with tumors harboring activating BRAF mutations in these trials exhibit some degree of tumor reduction, even if they do not meet the criteria for an objective clinical response." (PMID 24733413, 2014). "While basal phosphorylation profiles were similar in BRAF wild-type and BRAF(V600E) tumors, analysis with ex-vivo vemurafenib treatment identified a subset of 40 kinase substrates showing stronger inhibition in BRAF(V600E) tumor lysates, distinguishing the BRAF wild-type and BRAF(V600E) tumors." (PMID 24023633, 2013). "For specimens with a low content of tumor tissue, the DNA based protocols thus might not be sensitive enough to detect the BRAF mutations." (PMID 24298448, 2013). "However clinical effect may be linked to the biological profile of the tumor since two patients, who presented with NSCLC and GIST and achieved SD, had tumors harboring BRAF G469A and PDGFRAD842V exon 18 mutations, respectively." (PMID 23530663, 2013). "However, other clinicopathological features, including tumor size and cervical lymph node metastasis, were not significantly different between patients with or without BRAF mutation." (PMID 23690767, 2013). "No tumor was found to harbor a BRAF V600E point mutation among the 83 evaluable cases." (PMID 23637996, 2013). "However, the tumor/normal log2 ratios of AXIN1, CREBBP, GSK3A, and NKD2 in the BRAF wildtype samples were low (−0.26 median, 0.12 standard deviation) compared with those in the BRAF mutated samples (−0.02 median, 0.12 standard deviation)." (PMID 23324568, 2013). "However, in microsatellite stable (MSS), but not in MSI tumours, an adverse prognostic impact of BRAF mutation was observed in unadjusted, but not in adjusted analysis." (PMID 24020794, 2013). "We recently reported CRC expressing a BRAF-mutated signature 6, which strongly overlaps with the methylation-based group of Hinoue 11, and a MSI-like gene expression group that captures the hypermutant tumours of TCGA 13, indicating the potential for identification of robust biological subgroups." (PMID 23836465, 2013). "However, about half of the cutaneous melanoma tumours do not harbour BRAF mutations, and even in patients with these mutations, responses to vemurafenib are transient, lasting a median of 6.7 months." (PMID 22127285, 2012). "Though controversial, some studies have found that these adverse clinical effects of BRAF are negated in CIMP+ tumours, suggesting the poor prognosis is not attributable to the BRAF mutation itself, but is probably attributable to the genetic pathway in which it occurs." (PMID 22997602, 2012). "RAS and several of its downstream effectors, including BRAF, have since been shown to be commonly mutated in broad range of human cancers and biological studies have confirmed that RAS pathway activation promotes tumor initiation, progression and metastatic spread in many contexts." (PMID 22768234, 2012). "Hence, c-Met and BRAF co-activation may increase tumor robustness and resistance to targeted therapy due to activation of multiple growth and survival pathways." (PMID 22745804, 2012).
tumor (continued). "Tumor tissues from 504 patients with diverse cancers referred to the Clinical Center for Targeted Therapy at MD Anderson Cancer Center starting in October 2008 were analyzed for PIK3CA, RAS (KRAS, NRAS), and BRAF mutations using polymerase chain reaction-based DNA sequencing." (PMID 21829508, 2011). "All BRAF mutant tumours were non-responders and all mutually exclusive from mutated KRAS." (PMID 21439039, 2011). "A number of LMP tumours lacking KRAS or BRAF mutations harboured genomic aberrations, indicating that different initiating events may be present in these tumours." (PMID 22163003, 2011). "Across tumor types, we demonstrated a higher prevalence of RAS (KRAS, NRAS) or BRAF mutations (47%) and KRAS mutations (38%) in patients with mutant PIK3CA compared to those with wtPIK3CA (mutant RAS or BRAF present in 24%, p = 0.001; mutant KRAS present in 16%, p = 0.001)." (PMID 21829508, 2011). "Six of 9 tumours with a BRAF mutation had no somatic APC mutation." (PMID 21901162, 2011). "There was no BRAF mutation in 280 (83.3%) tumours, and 260 (92.9%) of these tumours were MSS." (PMID 20051945, 2010). "Mayo Medical Laboratories (Rochester, MN) BRAF Mutation Analysis (V600E), Tumor (Unit Code 87980): The specimen requirements for this assay are an FFPE tumor tissue block or a single H&E-stained 5-μm slide with 10 unstained nonbaked slides with 5 slides, each with 5-μm and 10-μm-thick sections." (PMID 20972475, 2010). "Mutation of the BRAF oncogene in tumour tissue nearly excludes the possibility of LS." (PMID 20051945, 2010). "However, in our study we found that there were 2 metastatic lymph nodes that did not maintain the BRAF mutation present in the corresponding primary tumor, suggesting that BRAF mutations are not essential for metastatic spread to the lymph node in all tumors." (PMID 20233444, 2010). "Importantly, in all samples, analysis of germ line DNA by ARMS was negative for BRAF mutations, confirming that any BRAF mutations detected were tumour derived." (PMID 19861964, 2009). "These relatively rare mutations, as well as codons 12 and 13 mutations, are responsible for the oncogenic constitutive activation of RAS/RAF/MAPKs pathway and they might account for up to a 10% of resistant patients bearing KRAS codons 12 and 13 and BRAF wild-type tumours." (PMID 19603018, 2009). "Five cfDNA samples were positive for a BRAF mutation in which no tumour data were available." (PMID 19861964, 2009). "However a clear relationship between BRAF mutations and aggressive tumour behaviour has not been demonstrated in all studies, and the predictive value of BRAF mutations remains uncertain." (PMID 19578508, 2008). "However, the relationship between BRAF mutations and more aggressive tumour behaviour have not been confirmed in a number of other studies, and a high frequency of BRAF mutations has been reported in microcarcinomas with an excellent prognosis." (PMID 19578508, 2008). "Furthermore, inhibition of oncogenic BRAF induces tumour shrinkage in vivo." (PMID 18628967, 2008). "However an association between BRAF mutations and aggressive tumour behaviour has not been demonstrated in all populations, making the clinical relevance of this association uncertain." (PMID 17179987, 2007). "This analysis focussed on secondary RDT end points: changes in bi-dimensional tumour measurements from baseline after 12 weeks and overall tumour responses (WHO criteria) at week 24, progression-free survival (PFS), safety and biomarkers (BRAF, KRAS and NRAS mutational status)." (PMID 16880785, 2006). "However, the caution has to be exercised in confirming the benign nature of this tumor on the basis of absence of BRAF mutation." (PMID 16867191, 2006). "Among these, dysregulation of the epidermal growth factor receptor (EGFR), BRAF, and HER2 signaling pathways represents a central driver of tumor progression and therapeutic resistance." (PMID 41899309, 2026).
tumor (continued). "Tumor coagulative necrosis was observed only in the cases of yellow slough cases, and all cases were dMMR/MSI‐high and BRAF mt CRCs." (PMID 40548293, 2026). "Data from this study provides provocative evidence that, while BRAF+/−MEK inhibitor therapy produces an increase in overall and clonal T cell infiltrates, there is limited evidence for generation of new or persistent tumor immunity." (PMID 41514118, 2026). "By enhancing T cell accessibility to tumor cells, ECM‐targeting agents promote immune‐mediated suppression of resistant clones, thereby extending the efficacy window of BRAF/MEKi treatment." (PMID 40847444, 2025). "Their study revealed that targeting SRC and BRAF had an equivalent or better effect on tumor growth inhibition compared to targeting EGFR and BRAF, similar to our observations." (PMID 40481178, 2025). "Therapeutically, we show that pharmacologic inhibition of ECM organization, administered at the point of minimal tumor burden, restores CD8+ T cell infiltration and delays the emergence of BRAF/MEKi resistance in a CD8+ T cell–dependent manner." (PMID 40847444, 2025). "Vemurafenib served as a type I BRAF inhibitor control and as expected, pERK levels increased with vemurafenib concentration in all NF1-LOF tumor cell lines." (PMID 40111124, 2025). "These mutations may occur in receptors (e.g., KITKIT), effectors (BRAF, NRAS), or inhibitors (NF1, RASA2, CDKN2A, SPRED1) of the pathway, leading to proliferation of transformed melanocytes, abnormal differentiation, and persistent survival with impaired apoptosis of tumour cells." (PMID 41295253, 2025). "Extensive clinicopathologic data allowed us to adjust survival models for multiple variables such as tumor location, tumor grade, disease stage, lymphovascular invasion, MMR status, and BRAF status, strengthening the relevance of the findings." (PMID 40928327, 2025). "It is observed that BRAF/MEK/PI3K signaling encompassed all cancer hallmarks, which gave insights on how this axis can be aggressive in tumor growth and metastasis." (PMID 41009348, 2025). "If the average F1 score improved by more than 5%—as observed for genes like BRAF, ATRX, and NRAS— selected tumour types were utilized for downstream analysis." (PMID 40775769, 2025). "Another study investigating the combined effect of BRAF inhibitor (Debrafenib) and MEK inhibitor (Trametinib) found 75% tumor reduction by 5 months." (PMID 40004632, 2025). "Preclinical and clinical evidence suggest that combining RT with systemic therapies, including BRAF/MEK inhibitors and ICIs, can synergistically enhance anti-tumor immune responses and improve treatment outcomes." (PMID 40867277, 2025). "Considering that the patient’s tumor was mainly composed of MTC, it is recommended that the patient undergo RET and BRAF gene somatic testing to evaluate the prognosis and provide a basis for targeted therapy." (PMID 41323380, 2025). "This approach supports efficient tumor classification based on using KRAS, BRAF, NTRK, ERBB2, and PIK3CA as key markers, along with MSI status." (PMID 40647370, 2025). "We employed targeted next-generation sequencing to analyze seven actionable driver genes - EGFR, KRAS, NRAS, BRAF, ALK, ROS1, and PIK3CA - in formalin-fixed, paraffin-embedded tumor specimens from Vietnamese NSCLC patients." (PMID 40502411, 2025). "We examined gene expression and BRAF activation using the MPAS, which is a metric that provides insight into the aggressiveness of tumor cell growth and proliferation." (PMID 40869231, 2025). "This case highlights the potential efficacy of chemo-immunotherapy in BRAF wild-type ATC, especially when a rapid tumor reduction is required." (PMID 40727481, 2025).
tumor (continued). "If BRAF IHC is unavailable, MLH1 promoter hypermethylation studies can be performed on the tumor material." (PMID 41463230, 2025). "Combined small molecule inhibition with SHP2 and BRAF/MEK inhibitors increased the depth and durability of ERK suppression, inhibited growth, and killed tumor cells." (PMID 40900823, 2025). "Next-generation IHC for BRAF V600E and RAS Q61R have been employed to identify the molecular drivers of ATC, showing diffuse weak to moderate expression in the tumor cytoplasm." (PMID 40111709, 2025). "Here, we demonstrate an inhibitory effect of NF1-GRD (GAP-related domain, residues 1198–1509) fused with RAS-CAAX motif on tumor cell growth and ERK signaling in NF1-MPNST and further prove the growth dependency of NF1-MPNST cells on CRAF and BRAF." (PMID 41023593, 2025). "Although the precise mechanisms regulating intracellular signaling by VSIR are not yet fully understood, emerging evidence indicates that BRAF/MEK signaling pathways mediate VSIR signaling, promoting tumor development and reshaping the tumor microenvironment." (PMID 41417109, 2025). "BRAF, and other MAPK pathway inhibitors, while initially highly effective at reducing tumor burden, are subject to drug resistance." (PMID 40719625, 2025). "Stronger anticancer effect in animals with KRAS and BRAF mutant by decreasing intracellular glucose and energy production due to intracellular ROS accumulation and GAPDH inhibition compared wild type tumor (P < 0.05)." (PMID 40950984, 2025). "To understand the differences in pERK modulation in response to tovorafenib in the BRAF fusion versus NF1-LOF setting, we further evaluated pERK modulation in three NF1-LOF tumor cell lines in vitro." (PMID 40111124, 2025). "This is based in part on preclinical evidence suggesting that BRAF and MEK inhibition can modulate the tumor immune environment." (PMID 40564107, 2025). "Initial molecular characterization of the primary tumor demonstrated wild-type status for both RAS and BRAF, preserved dihydropyrimidine dehydrogenase (DPD) activity, and a microsatellite stable (MSS) phenotype." (PMID 40842629, 2025). "The present study uncovered a rare co-occurrence of KRAS (G13D) and BRAF (V600E) alterations in CRC, highlighting tumor heterogeneity and challenging the assumption that these mutations are mutually exclusive within the studied ethnicity." (PMID 40949797, 2025). "This was consistent with clinical observations, such as higher rates of RAI-resistance in BRAF-positive tumours and follicular architecture in RAS- and PAX8::PPARG-positive tumours." (PMID 40361475, 2025). "In both cases, BRAF and MEK inhibition resulted in deep tumor response; however, disease progression was noted 15 and 7 months, respectively, from TT initiation." (PMID 41373618, 2025). "We confirmed the presence of both BRAF V600E and RET S649L in this earlier metastasis, indicating that RET S649L was an early event in tumor progression." (PMID 40756116, 2025). "Additionally, other biomarkers—including driver mutations (e.g., KRAS/BRAF), immune cell infiltration, and tumor microenvironment features—were not evaluated but may further elucidate response heterogeneity." (PMID 40255436, 2025). "The remarkable improvements in tumor response, PFS, and OS shown with cetuximab and panitumumab have raised the possibility of preserving EGFR antibodies for left-sided RAS/BRAF WT tumors." (PMID 41458799, 2025).
tumor (continued). "Preclinical models showed that combining BRAF inhibitors with MEK inhibitors achieves more durable pathway blockade, translating into prolonged tumor control and survival benefits in vivo." (PMID 40668344, 2025). "This vertical inhibition of the MAPK pathway at multiple levels, BRAF, MEK, and EGFR, provides more sustained suppression of tumor-promoting signals, resulting in improved antitumor efficacy." (PMID 40688855, 2025). "Our study underscores the complexity of CRC and the pivotal role of KRAS, BRAF, and PIK3CA variations in tumor progression and outcomes in Iraq's Kurdistan Region, highlighting the importance of molecular profiling in clinical care." (PMID 40949797, 2025). "These cases show that targeted neoadjuvant treatment strategy results in rapid tumor regression, pathological remission, and reduced stage in patients with potentially resectable stage IIIA BRAF V600E tumors." (PMID 41480531, 2025). "Based on the phenotypic and cell composition differences between BRAF-mutant and BRAF-wild-type CRC, we wanted to determine differences in immune cell composition between the two tumor types." (PMID 41039118, 2025). "Fifth, key prognostic factors such as PS and tumor molecular status (RAS, BRAF, MSI) were unavailable, limiting interpretability." (PMID 40447850, 2025). "By inhibiting BRAF, these drugs effectively block the MAPK/ERK signaling pathway, suppressing tumor cell proliferation and survival." (PMID 40696244, 2025). "The OS differences according to primary tumour location and molecular subgroups were seen in the actively treated groups, but interestingly also in the BSC group, for BRAF-V600Emt." (PMID 40437037, 2025). "Moreover, important molecular markers, such as KRAS, NRAS, and BRAF mutations, could not be evaluated, thereby restricting the ability to analyze the impact of tumor biology on survival comprehensively." (PMID 41517497, 2025). "the BRAF-driven MAPK pathway can upregulate TERT promoter activity, while TERT cooperates with mutant BRAF to drive tumor dedifferentiation and progression through mechanisms such as the modulation of ribosomal biogenesis." (PMID 41306438, 2025). "Overall, these results support that KU757 overcomes some of the pathways driving BRAF and MEK inhibitor resistance by downregulating key tumour‐promoting genes and upregulating tumour suppressors, several of which are drivers of MAPK resistance." (PMID 40135438, 2025). "Their studies demonstrated that combining BRAF and FAK inhibition in patient-derived CM xenografts led to prolonged tumor control, even after resistance to BRAFi developed." (PMID 39922199, 2025). "The multivariable models were adjusted for common prognostic factors, such as disease stage, lymphovascular invasion, tumour budding, MMR status, and BRAF status." (PMID 40055484, 2025). "Then, we measured the expression levels of MITF, BRAF and NRAS in the annotated cell types, which revealed increased expression of the two former genes in the tumour cells, compared to the microenvironment." (PMID 41168392, 2025). "Avutometinib is a RAF/MEK clamp that induces formation of inactive complexes of MEK with ARAF, BRAF, and CRAF, which leads to more complete and durable anti-tumor responses through maximal MAPK pathway inhibition." (PMID 39922199, 2025). "A recently published study reported that TWEAK enhanced tumor invasion in the SW48 colorectal cell line, which is wild‐type for both RAS and BRAF." (PMID 40629930, 2025).